HOXA10 (homeobox A10)
Diseases named in the same sentence as HOXA10 in open-access papers (continued):
Sharing a sentence is not in itself a finding about the gene and the disease.
cancer (continued). "Various pathways have been implicated in cancer tumorigenesis, cancer cell proliferation, migration and invasion, including regulation of the miR-329-3p/ALDOA axis, modulation of the miR-101/EZH2 axis, modulation of the miR-411-3p/HOXA10 pathway, and others." (PMID 38203269, 2023). "HOXA10 is a transcription factor involved in cell proliferation and apoptosis of various cancers." (PMID 36979165, 2023). "Moreover, given the potential role of HOXA10, the regulation of HOXA10 expression involved in carcinogenesis and cancer inhibition, which should be explored in further investigation." (PMID 36407869, 2022). "Likewise, the buccal mucosa-derived H157 (RRID: CVCL_2468) cancer cell lines showed overexpression of HOXA10, HOXC6, HOXC9, HOXC10 and HOXD11 which was consistent with the cancer of the buccal mucosa." (PMID 35710803, 2022). "PROM1, LGALS1, CD44, FUT4 and HOXA10 were identified as hub genes, which were involved in focal adhesion, calcium-dependent phospholipid binding, connective tissue development and transcriptional misregulation in cancer." (PMID 32347296, 2020). "Among the homeobox family genes, aberrant HOXA10 expressions have been implicated in numerous other types of cancers but not yet described in TGCT." (PMID 30581773, 2018). "Both up-regulation and down-regulation of HOXA10 expression have been associated with cellular processes implicated in cancer, including proliferation, apoptosis, epithelial–mesenchymal transition (EMT) and treatment resistance, which include the relation between HOXA10 and EC." (PMID 29618950, 2018). "Moreover, HOXA10 plays a cancer-promoting role in HNSCC cells." (PMID 33869744, 2021). "Interestingly, the roles of HOXA10 are complex among different types of cancers." (PMID 30581773, 2018). "The reduction in cell viability induced by MIR494 has been observed in other cancer types; indeed, several MIR494 targets have been thus far identified which are associated with reduced cellular survival including IGF2, c-KIT, HOXA10, CLPTM1L, SCGN, CXCR4, and c-myc." (PMID 26794413, 2016). "Thus, it is possible that Trop2 downregulation by HOXA10 may decrease NF-κB activation, which can thus decrease the NF-κB-binding to the HOXA10 promoter, which could lead to a decrease in cancer progression." (PMID 26000093, 2015). "Collectively, OSCC cancer cells can upregulate RUNX2 isoform II to inhibit ferroptosis and apoptosis and facilitate tumorigenesis through the novel HOXA10/RUNX2 isoform II/PRDX2 pathway." (PMID 40498062, 2025). "In terms of angiogenesis and cancer promotion, the effect of BHT is controversial; it was recently reported to limit angiogenesis by targeting COX-2, HOXA-10, and MMP-9." (PMID 39856999, 2025). "In bladder cancer, HOXA10 can upregulate MMP-3 and promote the invasion and proliferation of cancer cells." (PMID 36407869, 2022). "miR-195-5p has excellent antitumor effects via inhibiting cancer cell growth, invasion, and migration, arresting the cell cycle, promoting apoptosis, and sensitizing LUAD cells to X-ray irradiation by targeting HOXA10." (PMID 34925694, 2021). "HOXA10, a member of HOX genes, is involved in regulating differentiation and progression in several cancer types." (PMID 31763673, 2019). "In this study pathways enriched for demethylation include pathways in cancer, WNT signalling, and apoptosis, and some demethylated genes such as HOXA10 and RASSF1A correlated with progression free survival." (PMID 29373959, 2018). "Several target genes of miR-204, including HOXA10, MEIS1, FOXC1, MAP1LC3B, BCL2, NTRK2, SOX4 and EphB2, have been identified in different cancers." (PMID 26710269, 2015). "The results showed that some HOX genes in pan-cancer had significant strong correlation (R≥0.8): HOXA9 with HOXA10, HOXB5 with HOXB6 and HOXB8, HOXB8 with HOXB6 and HOXB9, HOXB3 with HOXB4 and HOXB5 and HOXB6, HOXC8 with HOXC9, HOXC9 with HOXC10, HOXD10 with HOXD11." (PMID 39980564, 2025).
cancer (continued). "Notably, six genes—MLLT3, MEIS1, PBX1, PBX3, HOXA10, KMT2A—were found to play a role in transcriptional dysregulation in cancer." (PMID 35743243, 2022). "There were 121 genes up-regulated that were overrepresented in the transcriptional misregulation in cancer pathway (KEGG:05202; P = 5.9 × 10−4), including chromatin regulator HMGA2 (Log2FC = 1.14; P = 2.9 × 10−3) and transcription factor HOXA10 (Log2FC = 1.03; P = 2.98 × 10−5)." (PMID 34069294, 2021). "Thus, inhibition of HOXA10 can downregulate EGR1, PTEN, and Rad51 paralogs in serial order to interfere with the HR system of cancer cells, making the cancer cell more vulnerable to temozolomide treatment." (PMID 25061500, 2014). "Using PPI analysis, the critical pathway of functional genes was found involved in the hematopoietic cell lineage and transcriptional misregulation in cancer, including HOXA10, MEIS1, FLT3, CD14, PROM1, RUNX2, and RUNX1 (data not shown), indicating the dominant roles of HOXA and MEIS1 in MLL-R ALL." (PMID 36276286, 2022). "Indeed it has been reported that HOXA10 is not regulated by miR-135a in MCF-7 cells which is in contrast to our results for other cancer cell lines tested." (PMID 22439757, 2012).
infection (3 papers, 2011 to 2021). The state of being infected such as from the introduction of a foreign agent such as serum, vaccine, antigenic substance or organism. "Similarly, infection with the same lentiviral shRNAs also markedly inhibited the colony formation by Hoxa10-immortalized cells, suggesting that Myb expression is also critical for Hoxa10-induced self-renewal." (PMID 29228732, 2017). "qRT-PCR successfully validated the infection efficiency of LINC00461, miR-195, and HOXA10." (PMID 33869744, 2021). "The down-regulated miR-29b and miR-29a are both or each connected to up-regulated SMARCE1, HBO1, NKX6-1, HOXA10, HBP1, OTUD4, that could be further considered as potent targets during infection." (PMID 21408164, 2011).
cardiovascular diseases (2 papers, 2021 to 2023). "HOXa is involved in the regulation of embryonic development, cell differentiation, cell cycle, apoptosis, and other biological processes, and HOXa10 is closely associated with the occurrence and development of cardiovascular diseases." (PMID 37569470, 2023). "Recently, the prominent role of the miR-27a-3p/HOXa10 pathway in the regulation of cardiovascular diseases has been observed in multiple studies." (PMID 37569470, 2023).
HOXA10 also shares sentences with these, for which no sentence is quoted: genetic disease (2 papers); melanoma (2); non-small cell lung carcinoma (2); abortion (1); adenocarcinoma (1); adrenal tumour (1); Arrhythmia (1); astrocytoma (1); basal cell carcinoma (1); breast tumor (1); chronic myelogenous leukemia (1); colonic carcinoma (1); congenital heart defects (1); diffuse astrocytoma (1); endometrial disorder (1); esophageal cancer (1); fertility disorders (1); gastrointestinal tumors (1); gynecological diseases (1); heart failure (1); hemangiosarcomas (1); Hyperinsulinemia (1); hypertrophy (1); invasive ductal carcinoma (1); keloid (1); laryngeal squamous cell carcinoma (1); lung squamous cell carcinoma (1); metabolic disorders (1); mouth neoplasms (1); mucinous tumours (1).
A further 18 diseases each share a sentence with HOXA10 in 1 paper.